GATA2 (GATA binding protein 2)
Diseases named in the same sentence as GATA2 in open-access papers (continued):
Sharing a sentence is not in itself a finding about the gene and the disease.
sickle cell disease (1 paper, 2024). Sickle cell anemias are chronic hemolytic diseases that may induce three types of acute accidents: severe anemia, severe bacterial infections, and ischemic vasoocclusive accidents (VOA) caused by sickle-shaped red blood cells obstructing small blood vessels and capillaries. "Benign indications for HSCT include sickle cell disease and genetic mutations leading to immunodeficiency diseases, i.e. GATA2, STAT3, DOCK8, PI3K gene mutations." (PMID 38756303, 2024).
skin aging (1 paper, 2021). The gradual irreversible changes in structure of skin that occur as a result of the passage of time.. "After GATA2 was activated, target gene BCL2 was upregulated to inhibit cell-cycle arrest and apoptosis in both middle-aged and elderly skin aging." (PMID 34073305, 2021).
small cell lung carcinoma (1 paper, 2021). Small cell lung cancer (SCLC) is a highly aggressive malignant neoplasm, accounting for 10-15% of lung cancer cases, characterized byrapid growth, and early metastasis. "Finally, we show that SMAD3, ZNF217, KLF13, GATA2, GATA3, KLF7, and PHOX2B are components of CRCs in other cancers, including DLBCL, pancreatic, gastric, breast, and small cell lung cancer." (PMID 35201514, 2021).
smooth muscle tumor (1 paper, 2017). A benign or malignant myomatous neoplasm arising from smooth muscle. "Two patients with GATA2 insufficiency have been reported with EBV-positive smooth muscle tumors." (PMID 29375553, 2017).
squamous cell lung carcinoma (1 paper, 2021). A carcinoma arising from squamous bronchial epithelial cells. "Furthermore, the alteration rates of GATA2/4/6 were 12, 12, and 6%, respectively in squamous cell lung carcinoma." (PMID 34093794, 2021).
Stargardt disease (1 paper, 2022). "This study revealed that several ABCA4 variants found in patients with Stargardt disease could affect ABCA4 expression, and common variants of the ABCA4 proximal promoter alter the ABCA4 transcriptional activity, which is regulated by GATA-2 and HLF." (PMID 36566289, 2022).
Stroke (1 paper, 2025). Sudden impairment of blood flow to a part of the brain due to occlusion or rupture of an artery to the brain. "For example, ASO-based drugs have already shown clinical success in other neurological and cardiovascular conditions, suggesting that RNA-based therapeutics could provide feasible intervention strategies for modulating GATA2/IRF7-driven gene networks in stroke." (PMID 40963808, 2025). "Therefore, the upregulation of Fos through the actions of Gata2 and Jund may have mediated the differentiation of endothelial cells into the critical aEC_cluster, therefore impacting the development of large atherosclerotic strokes." (PMID 40963808, 2025).
T-cell leukemia (1 paper, 2014). A malignant disease of the T-lymphocytes in the bone marrow, thymus, and/or blood. "GATA2 and GATA1 are implicated at many (up to 90%) of the TAL1-bound sites in normal hematopoietic cells, and GATA3 along with ETS1 and RUNX1 can direct TAL1 binding when it is aberrantly expressed in T-cell leukemias." (PMID 25319994, 2014).
thrombosis (1 paper, 2022). "A history of thrombosis has been reported in GATA2 deficiency, related to cerebrovascular accidents, deep vein thrombosis, pulmonary embolism, and portal vein thrombosis." (PMID 35356204, 2022).
thyrotroph adenomas (1 paper, 2020). "It is interesting to note that although the tumor did not have an adenomatous component, the present case had comparable specific-lineage transcription factors to that of thyrotroph adenomas such as Pit-1 and GATA-2; this case also exhibited specific neuronal differentiation." (PMID 32706866, 2020).
ulcerative colitis (1 paper, 2025). An inflammatory bowel disease involving the mucosal surface of the large intestine and rectum. "In this study, we identified FOXC1, GABPA, GATA2, and SUPT5H as key transcription factors implicated in the development of ulcerative colitis (UC) through the regulation of gene expression involved in inflammation, immune response, and epithelial barrier integrity." (PMID 41300749, 2025).
uterine serous carcinoma (1 paper, 2025). "Loss of GATA2 expression leads to uterine serous carcinoma invasion and metastasis." (PMID 40168074, 2025). "Routine GATA2 immunohistochemistry predicts cancer recurrence and patient survival in FIGO stage I uterine serous carcinoma." (PMID 40168074, 2025).
cancer (105 papers, 2010 to 2025). A tumor composed of atypical neoplastic, often pleomorphic cells that invade other tissues. "HOXC13 and GATA2 have been linked to a poor prognosis and aggressive phenotypes in a number of cancer lineages." (PMID 40858590, 2025). "To these, we applied a prioritization scheme that gave greater weight to genes based on degree of reduced expression after GATA2 depletion, size of the associated GATA2 occupancy peak, and published involvement in cancer progression." (PMID 40168074, 2025). "This case broadens the spectrum of solid cancers linked to GATA2‐deficiency and emphasizes the importance of considering underlying genetic causes in atypical presentations of cancer." (PMID 39614632, 2024). "The TFBIND software identified GATA2 as a transcription factor potentially associated with cancer specificity when simultaneously present with both the mutations in pGAPE." (PMID 35326649, 2022). "TFBIND software predicted GATA2 as an important transcription factor involved in defining cancer specificity when both mutations were present in the pGADD." (PMID 35326649, 2022). "A mechanistic link between RAS, which harbors activating mutations in 30% of all human cancers, and GATA2 has recently been uncovered." (PMID 29029492, 2017). "Moreover, exosomal miR-1304-3p, through the targeting of GATA2, a transcription factor involved in stem cell maintenance, was seen to activate cancer-associated adipocytes and induce the release of lipids, fueling cancer cell growth." (PMID 40691627, 2025). "The association between GATA2 and cancer is especially significant." (PMID 41154393, 2025). "Xenopus Ventx1.1 could be a novel therapeutic pathway to target Ventx- and GATA2-associated cancers." (PMID 35269883, 2022). "Taken together, introducing specific point mutations in a rat min-GADD34-Prom converts this non-cancer-specific promoter into a cancer-selective promoter, and the addition of GATA2 with existing AP1 and PEA3 transcription factors enhances further cancer-selective activity of the GAPE-Prom." (PMID 35326649, 2022). "Additionally, we identified a GATA2 transcription factor binding site, promoting cancer specificity when both min-PEG-Prom mutations are present in the GAPE-Prom." (PMID 35326649, 2022). "However, attempt to direct targeting GATA2 is still unavailable owing to the deficiency of its biological mechanisms and 3D structure information, and represent as an overall difficulty in targeting transcription factors in cancer." (PMID 37550764, 2023). "GATA2 has been shown to play a pivotal role in promoting metastasis and tumor progression across various cancers." (PMID 41514651, 2025). "Functional studies revealed that silencing GATA2 resulted in a pronounced decrease in cancer cell stemness and metastatic ability." (PMID 41514651, 2025). "Patients with pathogenic variants in the GATA Binding Protein 2 (GATA2), a hematopoietic transcription factor, are at risk for human papillomavirus-related (HPV) anogenital cancer at younger than expected ages." (PMID 39267745, 2024). "To investigate the possibility of cancer-promoting gene mutations in GC MDR, PCR amplification and Sanger sequencing were performed on all exons of CGA, GATA2, and EGFR in the cell lines we used." (PMID 38960034, 2024). "Female patients with GATA2 haploinsufficiency exhibit a heightened risk for severe, extensive, difficult to treat HPV disease and develop anogenital cancer at younger than expected ages compared to the general population." (PMID 39267745, 2024). "It was previously reported that GATA2 was consistently amplified in human tumors, mouse models of cancer, and the mouse embryo fibroblasts (MEF) immortalization system." (PMID 37550764, 2023). "The identified TFs, such as FOXC1, FOXL1, POU2F2, NFIC, NFkB1, MEF2A, GATA2, and E2F1, are mainly associated with different types of cancers and congenital disorders." (PMID 37026010, 2023).
cancer (continued). "We also found that a transcription factor and MYC target, GATA2, is a downstream target for the anti-cancer effects of the WS6 analogues." (PMID 36980710, 2023). "Introduction of ST6GALNAC5 significantly reversed the compromised cancer cell invasiveness in DU145 cells with GATA2 deficiency, indicating that ST6GALNAC6 was an important target to GATA2 in cancer cell invasion." (PMID 37468844, 2023). "GATA2 knockdown in DU145 cells significantly reduced the invasion capacity of cancer cells (p < 0.001)." (PMID 37468844, 2023). "Only three genes—ACTB, CSF3R, and GATA2—were identified in both the DEA and mutational analysis, which highlights their possible significance in cancer and disease development." (PMID 36497424, 2022). "GATA2 expression was enhanced in all of the cancer cell lines tested in comparison with their normal counterparts." (PMID 35326649, 2022). "Taken together, these results indicate that cancer cell-derived exosomal miR-425-3p inhibits preadipocyte proliferation and differentiation through targeting related regulating genes such as GATA2, IGFBP4, MMP15, and CEBPA." (PMID 35941833, 2022). "The mRNA expression level of GATA1 and GATA2 in OC listed the moderate highest among all cancer types using the CCLE analysis." (PMID 35488350, 2022). "Collectively, these results advocate that pGAPE/pPEG binding to GATA2 is higher in cancer cells compared to normal cells, and when GATA2 expression is changed in these cells, binding is also altered." (PMID 35326649, 2022). "We found that the GATA2 knockdown enhanced adipogenesis, and the CM of adipocytes with GATA2 knockdown significantly promoted cancer cell proliferation." (PMID 36517516, 2022). "We find that exosomal miR-1304-3p is incorporated into adipocytes and directly targeted anti-adipogenic factor GATA2, followed by promoting secretion of triglycerides, which fuels cancer cell growth." (PMID 36517516, 2022). "In order to compare GATA2 expression in cancers, we determined GATA2 protein levels in different cancer cell lines by Western blotting." (PMID 35326649, 2022). "In the three established cancer cell lines, LNCaP, 22Rv1 and VCaP, GATA2 was the predominant GATA factor, although the expressions in 22Rv1 of both isoforms and transcript variants were lower than in the two other cell lines." (PMID 35203681, 2022). "This demonstrates that GATA2 is an important transcription factor, which regulates pGAPE activity selectively in cancer cells." (PMID 35326649, 2022). "ESR1, TOR1AIP1, STAT1, COL1A1 were identified as high expression, while EGFR, AR, GATA2 were identified as a low expression in both cancer types." (PMID 33907495, 2021). "Evidence supports the potential of GATA2 as an early cancer detection marker and a good prognostic factor in NB, with high GATA2-expressing patient groups displaying greater OS compared to those with low levels of GATA2." (PMID 35201514, 2021). "Having discovered this capacity of dilazep to suppress several well-known PC drivers, we propose that GATA2 inhibition would be expected to affect several hallmarks of cancer." (PMID 34636746, 2021). "The ICC assay results indicated that the expression of erythroid differentiation-related proteins, including HIF-1α, EPO, c-Myc, GATA-1, and GATA-2, was increased in cancer cells treated with ATO." (PMID 34676163, 2021). "For instance, KRAS oncogene mutations are common in various cancers and had been found that ATR or GATA2 transcription factor inhibition is synthetically lethal." (PMID 32883316, 2020). "The observations reinforced that GATA2 controls haematopoiesis and therefore its disruption results in cancer in affected cell lineages." (PMID 31379882, 2019). "Although less is known about the direct role of GATA2 in cancer, a subset of human chronic myelogenous leukemia (CML) patients harbor two mutations in the zinc finger domain of GATA2." (PMID 31614829, 2019).
cancer (continued). "Our results also raise the possibility that other semaphorins or their receptors fall under AR, GATA2, or FOXA1 regulation, especially given that many semaphorin family members are implicated in cancer." (PMID 28038451, 2017). "These raise the possibility of regulating GATA2-involved pathways for cancer therapeutic strategies." (PMID 26287967, 2015). "Its C allele has been associated with cancer, suggesting that it interferes with the binding of the GATA-1 and GATA-2 transcription factors to the estrogen receptor." (PMID 23574728, 2013). "Similarly, GATA2 plays a multifaceted role by exacerbating metabolic dysfunction through inflammatory responses, while also facilitating cancer cell invasion, survival, angiogenesis, and tumor growth." (PMID 40127075, 2025). "GATA2 status predicts cancer recurrence and survival in FIGO stage I USC." (PMID 40168074, 2025). "Notably, these recurrent SLRs were associated with genes known to be implicated in cancer, as evidenced by the Catalogue of Somatic Mutations in Cancer (COSMIC), including RALGDS, BCR, SH2B3, LMNA, and GATA2." (PMID 40193528, 2025). "GATA2 has been shown to function as an oncoprotein in many other cancers." (PMID 36980710, 2023). "However, further studies are needed to determine the molecular mechanism for how GATA2 mediates the anti-cancer effects of these compounds." (PMID 36980710, 2023). "Considering these results, we hypothesized that GATA2 might directly or indirectly regulate pGAPE/pPEG expression levels in cancer cells." (PMID 35326649, 2022). "Additionally, we found that GATA2 overexpression enhanced GAPE cancer specificity, and conversely, GATA2 inhibition reduced GAPE cancer specificity." (PMID 35326649, 2022). "Given that apoptosis-resistant cancer cells acquire stem cell–like properties, we tested whether chemotherapy induces the autoregulation of GATA2." (PMID 35289315, 2022). "Furthermore, two cells displayed high expression of stem cell markers, GATA2 and Pax6, suggesting that they were cancer stem‐like cells (red arrowheads)." (PMID 33932101, 2021). "GATA2 and MCM4 mutations are found in NKD patients with cancer." (PMID 31379882, 2019). "Biological variables associated to a high risk of progression included CIP2A levels, the expression levels of the polycomb group BMI1 gene, the activation of beta-catenin, specific gene signatures, and mutations in cancer-associated genes such as ASXL1, IKZF1, RUNX1, SETD1B, GATA2, MLL, and UBE2A." (PMID 31709190, 2019). "The cancers have been observed in NKD patients with GATA2 and MCM4 mutations although not in patients with IRF8, RTEL1, and FCGR3A mutations." (PMID 31379882, 2019). "Thus, our data strongly suggest that GATA2 and c‐JUN are TFs in addition to FOXA1 and HOXB13 that associate with ARBSs and regulate AR binding selectively in normal and cancer cells." (PMID 31520575, 2019). "In addition, this polymorphism affects binding to 5 proteins implicated in cancer development (CCNT2, GATA2, TAL1, KAP1 and CTCF)." (PMID 27437873, 2016). "Recently, GATA-2 and GATA-3 were found to be associated with tumorigenesis in various cancers." (PMID 27528231, 2016). "However, the role of GATA2 genotypes in cancer prognosis remains largely unexplored in solid tumors." (PMID 26287967, 2015). "Interestingly, FOG1 interacts with the GATA transcription factors, which include GATA2, which is essential for proliferation of cancer cells carrying oncogenic K-Ras." (PMID 24806839, 2014). "LUAD exhibited a particularly high number of 7 mutated genes with significant co-occurrence with CNAs compared to other cancer types – including EGFR, GATA2, GBA, GLI3, KAT6A, KRAS and NOTCH3." (PMID 41415395, 2025).